IDE (insulin degrading enzyme)
Diseases named in the same sentence as IDE in open-access papers (continued):
Sharing a sentence is not in itself a finding about the gene and the disease.
cancer (5 papers, 2014 to 2023). A tumor composed of atypical neoplastic, often pleomorphic cells that invade other tissues. "IDE has been implicated in the proliferation and survival of cancer cells." (PMID 35406791, 2022). "Known as the main enzyme responsible for the degradation of insulin, an essential growth factor for healthy cells and cancer cells, IDE has also been shown to behave like a chaperone and interact with the proteasome." (PMID 35406791, 2022). "IDE has been thus shown to hydrolyze more than 15 different substrates that are involved in cancer pathophysiology." (PMID 35406791, 2022). "In this study, knockout of IDE in cancer cells had a minimal effect on cell cycle profile, cell migration and cell growth, but upon serum starvation, the absence of IDE decreased proliferation and migration." (PMID 35406791, 2022). "IDE behaves primarily as a proteolytic enzyme involved in the degradation of many substrates, amongst which several are of interest in cancer biology." (PMID 35406791, 2022). "Along with the activity of the modulators, these structural data could help rationalize which of the roles of IDE in cancer depend on its catalytic activity or come from another function." (PMID 35406791, 2022). "All these results point towards IDE as a potential target in cancer." (PMID 35406791, 2022). "Still, the exact role of IDE in the physiopathology of cancer remains to be elucidated." (PMID 35406791, 2022). "However, since IDE is a peptide processing protease, its role in antigen presentation, specifically in cancer, warrants further study." (PMID 35406791, 2022). "In three cancer cell lines, it was shown that IDE interacts with this efflux pump." (PMID 35406791, 2022). "Actually, studies on the role of GOPC, PAEP and IDE in STAD are mostly lacking, but they all have important roles in other cancer types." (PMID 35859893, 2022).
tumor (3 papers, 2014 to 2022). "Based on published studies, one could argue that this effect might be mediated by an interaction between IDE and the retinoblastoma protein (pRb), a tumour suppressor that inhibits cell-cycle progression at the G1/S transition when interacting with E2F transcription factors." (PMID 35652923, 2022). "Recently insulin-degrading enzyme (IDE) was shown to produce an antigenic peptide derived from the tumor antigen MAGE-A3 in an entirely proteasome-independent manner, raising the question of the global impact of IDE in MHC class I antigen processing." (PMID 24516642, 2014).
neurodegenerative disease (2 papers, 2022 to 2025). A disorder of the central nervous system characterized by gradual and progressive loss of neural tissue and neurologic function. "A deeper understanding of IDE’s role in the context of both metabolic and neurodegenerative diseases may provide valuable insights for the development of new therapeutic strategies." (PMID 40724942, 2025).
adenocarcinoma (1 paper, 2022). A common cancer characterized by the presence of malignant glandular cells. "More interestingly, HEPV and HECC were also influential in diminishing the expression of IDE in adenocarcinoma cells, suggesting that the anti-proliferative effects of the extracts could be mediated by IDE down-regulation." (PMID 36249459, 2022).
tumors of the CNS (1 paper, 2014). "More recently, it has been reported that IDE, apart from regulating insulin and Aβ peptides levels, is overexpressed in vivo in tumors of the CNS, and a novel role for IDE as a heat shock protein has also been proposed." (PMID 25247577, 2014).
vasculopathy (1 paper, 2024). "Some of these include VZV leading to increased production of amyloid plaques either directly or through binding to insulin-degrading enzyme, subclinical inflammation of the central nervous system due to VZV invasion, VZV-induced vasculopathy, and induction of systemic inflammatory cytokines." (PMID 38271405, 2024).
IDE also shares sentences with these, for which no sentence is quoted: memory impairment (3 papers); metabolic disorders (3); metabolic syndrome (3); insulin-dependent diabetes (2); Parkinson disease (2); vascular dementia (2); autoimmune disease (1); bacterial meningitis (1); cognitive decline (1); diabetic foot ulcers (1); Hypercholesterolemia (1); malignant glioma (1); Nephropathy (1); neurodevelopmental disorder (1); neuropathy (1); Onset (1); retinopathy (1); Senile plaques (1).